TMEM171 (transmembrane protein 171)
Synonyms: PRP2
Tractability: Antibody: UniProt predicts a signal peptide or a membrane-spanning region. PROTAC: ubiquitination databases record sites on it.
Gene: Protein-coding gene on chromosome 5 (73,120,569 to 73,131,812, forward strand). Ensembl gene ENSG00000157111.
Subcellular location: Membrane
Gene Ontology:
Molecular function: protein binding
Cellular component: membrane
Genetic constraint (gnomAD): Loss-of-function variants: 16 observed, 19.77 expected, observed/expected ratio (o/e) 0.81, 90% interval 0.55 to 1.23. The upper end of that interval is the gene's LOEUF score, 1.23, which puts it in group 5 of 6, group 1 being the genes least tolerant of losing a copy. Missense variants: 429 observed, 430.64 expected, observed/expected ratio (o/e) 1, 90% interval 0.92 to 1.08. Synonymous variants: 153 observed, 170.75 expected, observed/expected ratio (o/e) 0.9, 90% interval 0.79 to 1.02.
Homologues: Orthologues: chimpanzee TMEM171 (99% identical), macaque TMEM171 (94% identical), pig TMEM171 (80% identical), mouse Tmem171 (75% identical), rat Tmem171 (74% identical), dog TMEM171 (73% identical), rabbit TMEM171 (72% identical), guinea pig TMEM171 (70% identical), tropical clawed frog tmem171 (49% identical).
Diseases named in the same sentence as TMEM171 in open-access papers:
TMEM171 is named in the same sentence as 3 diseases in open-access papers, as found by Europe PMC text mining. Sharing a sentence is not in itself a finding about the gene and the disease. The quoted sentences say what the papers report.
cancer (4 papers, 2019 to 2024). A tumor composed of atypical neoplastic, often pleomorphic cells that invade other tissues. "TMEM171 codes for a transmembrane protein that has been associated with different types of cancer, and TNPO1 codes for Transportin, a protein that participates in the nuclear transport of molecules." (PMID 38103737, 2024). "The 13 overexpressed genes were reported to play a role in RCC: PAX2, NAT8, GBA3, SLC22A2 other cancer types: AOC1, HAO2, TMEM27, cell death (NPR3) or kidney metabolism: TMEM171, CYS1." (PMID 31150395, 2019). "For ADAT3 and TMEM171, there is little published data on TMEM171 and ADAT3 function in cancer." (PMID 33976744, 2021).
TMEM171 also shares sentences with these, for which no sentence is quoted: myeloma (1 paper); tumour (1).